NUFIP2 (nuclear FMR1 interacting protein 2)
Description:
Binds RNA.
Synonyms: 82-FIP; KIAA1321; PIG1; MGC117262; 182-FIP; FIP-82; NUFP2
Tractability: PROTAC: UniProt records ubiquitination sites on it; ubiquitination databases record sites on it; its protein half-life has been measured.
Gene: Protein-coding gene on chromosome 17 (29,255,839 to 29,294,148, reverse strand). Ensembl gene ENSG00000108256.
Subcellular location: Nucleus; Cytoplasm; Cytoplasm, Stress granule
Subcellular location (Human Protein Atlas): Nucleoplasm; Cytosol; Nuclear bodies
Gene Ontology:
Molecular function: protein binding; RNA binding
Cellular component: cytoplasm; cytoplasmic stress granule; cytosol; membrane; nuclear body; nucleoplasm; nucleus; ribosome
Genetic constraint (gnomAD): Loss-of-function variants: 5 observed, 52.94 expected, observed/expected ratio (o/e) 0.0944, 90% interval 0.048 to 0.2. The upper end of that interval is the gene's LOEUF score, 0.2, which puts it in group 1 of 6, group 1 being the genes least tolerant of losing a copy. Missense variants: 798 observed, 835.58 expected, observed/expected ratio (o/e) 0.96, 90% interval 0.9 to 1.01. Synonymous variants: 313 observed, 307.39 expected, observed/expected ratio (o/e) 1.02, 90% interval 0.93 to 1.12.
Homologues: Orthologues: chimpanzee NUFIP2 (99% identical), macaque NUFIP2 (99% identical), rabbit NUFIP2 (96% identical), rat Nufip2 (94% identical), mouse Nufip2 (94% identical), dog NUFIP2 (93% identical), pig NUFIP2 (93% identical), guinea pig NUFIP2 (88% identical), tropical clawed frog nufip2 (55% identical).
Diseases named in the same sentence as NUFIP2 in open-access papers:
NUFIP2 is named in the same sentence as 11 diseases in open-access papers, as found by Europe PMC text mining. Sharing a sentence is not in itself a finding about the gene and the disease. The quoted sentences say what the papers report.
cognitive disorder (2 papers, 2023 to 2025). A disease affects cognitive processes. "Taken together, DHT inhibited REDOX damage and neuroinflammation in the hippocampus to alleviate cognitive disorders in mice with PNDs via activation of the mmu_circ_0001442/miR‐125a‐3p/NUFIP2 axis." (PMID 37550899, 2023). "In summary, this article demonstrated that DHT can inhibit REDOX damage and neuroinflammation by activating the mmu_circ_0001442/miR‐125a‐3p/NUFIP2 axis, thereby alleviating the occurrence of cognitive impairment in mice with perioperative neurocognitive impairment." (PMID 37550899, 2023).
Arthritis (1 paper, 2022). Inflammation of a joint. "Like NUFIP2, ANKH was also reported to be involved in the pathogenesis of arthritis, immune and inflammatory response." (PMID 36591247, 2022).
atrial fibrillation (1 paper, 2021). A disorder characterized by an electrocardiographic finding of a supraventricular arrhythmia characterized by the replacement of consistent P waves by rapid oscillations or fibrillatory waves that vary in size, shape and timing and are accompanied by an irregular ventricular response. "Trait associations were found for five loci: the SNV at TMEM44 was associated with diastolic blood pressure, SLC27A6 with red cell distribution, NKX2–5 with heart rate and atrial fibrillation, and finally NUFIP2 with mean platelet volume." (PMID 34274964, 2021).
infection (3 papers, 2016 to 2021). The state of being infected such as from the introduction of a foreign agent such as serum, vaccine, antigenic substance or organism. "The other target gene, NUFIP2, which encodes a nuclear fragile X mental retardation-interacting protein 2, is possibly regulated by the expression of hsa-miR-32-5p, hsa-miR-590-3p, and hsa-miR-193a-3p miRNAs through the infection of THP-1 Mø-like cells with H. capsulatum yeasts." (PMID 33477397, 2021). "The NUFIP2 gene contains 4 isoforms, with the infection reduced 00110828 specific reads (red boxed area)." (PMID 27354008, 2016).
NUFIP2 also shares sentences with these, for which no sentence is quoted: asthma (1 paper); Epileptic encephalopathy (1); immune disease (1); migraine (1); nervous system disorder (1); rheumatoid arthritis (1); tumour (1).